AIM2 (absent in melanoma 2)
Diseases named in the same sentence as AIM2 in open-access papers (continued):
Sharing a sentence is not in itself a finding about the gene and the disease.
cancer (continued). "Absent in melanoma 2 (AIM2) is an innate immune cytosolic DNA sensor best known as an inflammasome‐associated PRR, and has been implicated in numerous inflammatory diseases and cancers." (PMID 36967659, 2023). "Therefore, cGAS, STING, and AIM2 have attracted attention as drug discovery seeds in the cancer immunotherapy field." (PMID 37046775, 2023). "Notably, recent research underscores AIM2’s dual role in cancer progression and inflammasome activation, highlighting its influence on the advancement and evolution of tumors." (PMID 38186575, 2023). "In addition to activating inflammasomes for immune function, studies have found that AIM2 also has the dual effects of promoting or inhibiting cancer development." (PMID 37359371, 2023). "In different types of cancer, AIM2 also plays a pro-oncogenic or anti-cancerous role." (PMID 36386141, 2022). "The function of AIM2 inflammasomes in pan-cancer was analyzed at the single-cell level." (PMID 36248785, 2022). "Hypomethylation across cancers was observed for AIM2, CASP8, GZMA, and IL-1B." (PMID 36605187, 2022). "In fact, GSDMC, GSDMA, GSDMD, and AIM2 were the most upregulated genes across cancers." (PMID 36605187, 2022). "We further verified AIM2 inflammasome as a cancer suppressor in BLCA both in vitro and in vivo." (PMID 36386141, 2022). "Although the role of AIM2 have been reported in limited types of cancers." (PMID 36248785, 2022). "Overall, TTFields generate large cytosolic naked micronuclei clusters in GBM and other cancer cell types through focal disruption of the nuclear envelope, thereby recruiting cGAS and AIM2 to create a ripe condition for activation of their cognate inflammasomes." (PMID 35199647, 2022). "Some studies found that the AIM2 inflammasome was a double-edged sword in many cancers." (PMID 36248785, 2022). "AIM2 presented different functions in different kinds of malignant tumors." (PMID 36276158, 2022). "Although studies on AIM2 inflammasomes have been specifically reported in some cancers, its relationship with immunity remains unclear." (PMID 36248785, 2022). "Therefore, the role of AIM2 in tumorigenesis was bipartite, and its outcome depended on the type of cancer." (PMID 35847844, 2022). "LINC01207 upregulates LDHA expression to promote cell proliferation and migration and inhibits apoptosis and autophagy by acting as a ceRNA that sponges miR-1301-3p, whereas LINC00958 downregulates miR-4306 levels to activate a pyroptosis pathway mediated by AIM2 and promotes cancer cell survival." (PMID 35978835, 2022). "With the recent recognition of a critical role for cytosolic DNA sensors’ inflammasomes in stimulating antitumor immunity, the search for and development of pharmaceutical agonists of STING and AIM2 have been an active area of investigation in cancer immunotherapy." (PMID 35199647, 2022). "Varieties of inflammasome formation like NLRP1 (nod-like receptor protein 1), NLRP3 (nod-like receptor protein 3), AIM-2 (absent in melanoma 2), NLRC4 (nod-like receptor family CARD domain containing 4) cause cell pyroptosis in inflammatory diseases and cancers." (PMID 35165294, 2022). "Studying the application of AIM2 inflammasomes in different types of cancer may have important implications." (PMID 36248785, 2022). "Therefore, we used an experimental first-hand smoking mouse model in order to mimic and understand AIM2 pathway in a time-dependent manner before cancer establishes, focusing on the smoking status, collagen deposition, alveolar damage, typical of COPD." (PMID 34084280, 2021). "In addition to having a function in innate immunity, AIM2 is also known to be involved in the development and progression of cancers." (PMID 33859277, 2021). "However, AIM2 was also reported to act as oncogene in the development of several cancers, suggesting it is necessary to investigate the role of AIM2 in different cancers." (PMID 33842454, 2021).
cancer (continued). "Besides, caspases have also been reported to participate in AIM2-mediated cell death in cancer cells." (PMID 33842454, 2021). "Nowadays, the precise role of AIM2 inflammasome in cancer is still elusive." (PMID 34084280, 2021). "The specific mechanisms of action of AIM2 in these cancers remain obscure." (PMID 34721986, 2021). "AIM2 may play a unique role in different cancer types, and present study showed that AIM2 plays a cancer-promoting role in ccRCC." (PMID 34906145, 2021). "The results suggested that AIM2 might have a direct effect on the growth of cancer epithelial cells." (PMID 33391539, 2021). "In comparison, the role of AIM2 in cancer development is less clear." (PMID 33353088, 2020). "In different types of tumor tissue, the variation of AIM2 expression may play a role in the pathogenesis of various cancers." (PMID 32121297, 2020). "Moreover, inflammasome-independent roles of AIM2 in signaling pathways and biological processes related to cancer and other diseases are also well documented." (PMID 32906750, 2020). "In turn, the AIM2 inflammasome stimulates prostate hyperplasia and cancer development." (PMID 33014808, 2020). "And it was found that IFI16 and AIM2 were significantly upregulated in the patients with cancer." (PMID 32577124, 2020). "Thus, DNA-sensors TLR9 and AIM2 perform opposite functions to entail either survival (TLR9) of death (AIM2) of the cancer cells." (PMID 31205871, 2019). "Paradoxically, AIM2 is regarded as a tumor suppressor in various cancers." (PMID 31492049, 2019). "Apart from its role in host immune defense, AIM2 also acts as an oncogene in cancer." (PMID 31492049, 2019). "AIM2 was deregulated in several types of cancer and might represent a potential therapeutic target for cancer." (PMID 31492049, 2019). "Taken together, AIM2 might serve as a common danger sensor in different cancer cell types, which helps the host cells to be exempt from immune inflammation, and thus maintains the intracellular homeostasis and sanctity." (PMID 30160343, 2018). "There is recent evidence for the involvement of AIM2 in carcinogenesis, but the exact role of AIM2 in cancer progression remains unclear." (PMID 28526809, 2017). "Studies showed the expression of AIM2 was downregulated in hepatocrcinoma and the absence of AIM2 was more susceptible to cancer progression." (PMID 28360909, 2017). "Therefore, AIM2 can also regulate stem cells proliferation against cancer in an inflammasome-independent manner." (PMID 28360909, 2017). "Though the function of AIM2 in innate immunity is well accepted, its role in cancer is less clear." (PMID 27167192, 2016). "The activated AIM2 inflammasome in macrophages promotes the proteolytic cleavage and secretion of pro-inflammatory cytokines (IL-1β and IL-18) through the activation of caspase-1, leading to cell senescence, apoptosis and preventing cancer progression." (PMID 27806724, 2016). "Consequently, AIM2 may be a potential molecular target for cancer immunotherapy, and further studies are expected to reveal its application prospects in cancer therapy." (PMID 41811896, 2026). "Therefore, according to the cancer type, it is very important to understand whether AIM2 could represent a pharmacological tool in cancer." (PMID 40002808, 2025). "Follow-up research should therefore also include a deeper understanding of macrophage AIM2-triggered cancer cell death, specifically looking at pyroptosis-, apoptosis- and autophagic-driven mechanisms, to determine the effectiveness of rFIP-nha as an anti-cancer immunotherapeutic." (PMID 40356602, 2025). "Of particular note, the loss of AIM2 induced by Hepatitis B virus X protein (HBx) has been implicated in adverse clinical outcomes and facilitated HCC metastasis through the induction of EMT, a process pivotal for cancer cell dissemination and colonization at distant sites." (PMID 40386782, 2025).
cancer (continued). "Our data showed a clear rFIP-nha driven upregulation in AIM2 gene expression; in doing so rFIP-nha treated macrophages may become more sensitive in detecting cancer cell-secreted dsDNA and thus more effective in inducing cancer cell death." (PMID 40356602, 2025). "Thus, despite the great interest in understanding the interplay between cGAS and AIM2-dependent pathways in cancer, this review will focus on AIM2, elucidating its dual role according to cancer type, taking into consideration the current therapeutic strategies for targeting the AIM2 inflammasome." (PMID 40002808, 2025). "Therefore, our findings suggest that AIM2 might be a valuable biomarker for predicting the anti-cancer effectiveness of pembrolizumab and ipilimumab on the radioresistant/metastatic OSCC." (PMID 38166970, 2024). "Alternatively, it may be possible that artificial depletion of pDCs in experimental animal models potentiated the anti-cancer immune response through the activation of other damaged DNA-sensing pathways, i.e. AIM2 or cGAS-STING pathways, with DNA remaining in the TME." (PMID 37435086, 2023). "Our results show that DNA-RNA hybrids may be the trigger for AIM2 inflammasome in cancers." (PMID 37449203, 2023). "It is known that AIM2 can detect dsDNA released during the pathological attack and cellular perturbation, and its recognition of dsDNA leads to the assembly of AIM2 inflammasome and the occurrence of pyroptosis, which plays an important role in infectious diseases, inflammatory diseases, and cancer." (PMID 36845112, 2023). "The abrogation of AIM2 signaling, either in the AIM2-deficient mice or by a pharmacological inhibitor such as thalidomide, significantly reduced the incidence of drug-induced diarrhea without affecting the anti-cancer efficacy of CPT-11." (PMID 37191444, 2023). "Thus, an AIM2 siRNA nanovaccine that acts selectively on CD45+ cells could be a novel cancer immunotherapy." (PMID 37046775, 2023). "Hence, these studies link AIM2 with the PI3K–AKT–mTOR signaling pathway in cancer cells." (PMID 34697412, 2022). "However, there have been fewer studies on AIM2 inflammasomes in pan-cancer." (PMID 36248785, 2022). "Interestingly, except AIM2 was negatively associated with DLBC and CASP5 was negatively associated with COAD and READ in ESTIMATE score and stromal score, others were positively associated with cancers in the immune score, stromal score, and ESTIMATE score." (PMID 34906145, 2021). "Thus, further studies are required to elucidate the role of AIM2 in cancer." (PMID 33353088, 2020). "Therefore, AIM2 is essential for the regulation of innate immune responses and plays a central role in the pathogenesis of inflammatory diseases, autoimmune diseases, and cancers." (PMID 32903550, 2020). "Thus, suppression of HIF-1α by AIM2 may contribute to the restriction and reduction of cancer invasion of these HCC cells." (PMID 27167192, 2016). "Similar patterns of coding microsatellite instability in MMR-DCF and MMR-deficient cancers suggest that certain combinations of coding microsatellite mutations, including mutations of the HT001, AIM2 and BAX gene, may contribute to the progression of MMR-deficient lesions into MMR-deficient cancers." (PMID 25816162, 2015). "Furthermore, the extent of NLRC3 and AIM2 gene reduction was correlated with cancer progression." (PMID 26378020, 2015). "The authors found that the AIM2 gene expression was diminished in CRC patients and its absence was correlated to cancer progression." (PMID 40002808, 2025). "Upstream sensors like ZBP1, AIM2, and RIPK1, along with regulators identified in cancer-related PANoptosis studies, such as IRF1, ADAR, MAP3K7, and NFS1, were also incorporated for their significant regulatory roles." (PMID 39901195, 2025). "Therefore, Akt inhibitors could be rational drug design targets for AIM2-deficent cancers." (PMID 41291696, 2025).
cancer (continued). "A study demonstrated that overexpression of AIM2 played a significant role in the tumorigenesis of OSCC, leading to increased cancer cell migration, enhanced invasive capabilities, and promotion of EMT." (PMID 39744568, 2025). "Conversely, AIM2 can also facilitate cancer progression by promoting EMT and affecting the cell cycle, highlighting the complex role of AIM2 in cancer development." (PMID 39744568, 2025). "Recent advances have highlighted the potential of targeting inflammasome components such as sensor proteins (e.g., NLRP3, AIM2), adaptor proteins (e.g., ASC), caspase-1, and downstream cytokines IL-1β and IL-18—to modulate the immune response against cancer." (PMID 40155968, 2025). "In addition to what we know so far, highlighting the DNA sensor role of AIM2, further analysis of the impact of PUFA metabolites on AIM2 activity may provide different perspectives for therapeutic approaches targeting AIM2, especially in cancer accompanied by complex metabolic alterations." (PMID 39290706, 2024). "Thus, AIM2 could be a potential molecular target for cancer immunotherapies." (PMID 37046775, 2023). "AIM2, ZBP1, STAT1, and FAS mediate the immune response and play important roles in a variety of diseases, cancers, and infections." (PMID 37205113, 2023). "Significantly upregulated PRGs included PYCARD in 12 cancers; GSDMB in 10 cancers; IL18 in 9 cancers; GSDMD, CASP8, GZMB, and GPX4 in 8 cancers; AIM2 and CASP6 in 7 cancers; GZMA in 6 cancers; GSDME, CASP4 and DHX9 in 5 cancers; GSDMA and GSDMC in 4 cancers." (PMID 36605187, 2022). "GSDMC, GSDMD, GSDME, ZBP1, AIM2, DHX9 and NLRP3 demonstrated significant amplification across cancers." (PMID 36605187, 2022). "Therefore, AIM2 may play a unique role in different cancer types." (PMID 33828074, 2021). "Absent in melanoma 2 (AIM2), a member of the pyrin-HIN family proteins, plays various roles across different types of cancers." (PMID 33859277, 2021). "It is known that AIM2 regulates AKT signaling in colorectal cancer, and that AKT plays a vital role in modulating cancer cell proliferation and migration." (PMID 33859277, 2021). "When cancer cells were co-cultured with TAM, we found that the expression of NLRP3, AIM2, cleaved-caspase 1, and IL-1β was significantly upregulated." (PMID 34815793, 2021). "Absent in melanoma 2 (AIM2), as a member of the pyrin-HIN family proteins, plays contentious roles in different types of cancers." (PMID 33291082, 2020). "AIM2 has been suggested to play roles in several cancers, and the TRIM11-p62-autophagy axis attenuated AIM2 signaling." (PMID 32226386, 2020). "For evaluation of Ad‐CAIXpromotor‐AIM2 for cancer‐specific expression, E1A or AIM2 expression was detected by flow cytometry in OSRC‐2 cells infected with Ad‐Ctrl, Ad‐AIM2, Ad‐CAIXpromotor or Ad‐CAIXpromotor‐AIM2, respectively." (PMID 32725966, 2020). "TLR9 promotes survivability of cancer cells by activating the TLR9—MyD88 –NF-kB signaling pathway, whereas AIM2 induces apoptosis in cancer cells being a part of the inflammasome." (PMID 31205871, 2019). "ROS generation, DNA damage, cell cycle, expression of TLR9, AIM2, NF-kB, STAT3, and RNA for 44 genes affecting the cancer cell viability were evaluated." (PMID 31205871, 2019). "However, recent research suggests that AIM2 may also act as an oncogene in some cancers." (PMID 26290184, 2015). "We have done extensive analyses that revealed the potential value of NLR and AIM2 genes as biomarkers of CRC and cancer progression." (PMID 26378020, 2015). "This review primarily focuses on recent research regarding the diverse functions of AIM2 independent of the inflammasome in inflammatory responses, cell proliferation, apoptosis, and metastasis across various cancer types." (PMID 39744568, 2025).
cancer (continued). "Different studies have drawn different conclusions about the pro-cancer effects of AIM2 independent or independent of inflammasomes activation." (PMID 40386782, 2025). "Research has demonstrated that the AIM2 inflammasome not only plays a protective role in infectious diseases but also serves as a pivotal regulator in noninfectious conditions, such as cancer." (PMID 39222064, 2024). "Absent in melanoma 2 (AIM2), a novel identified inflammatory body, has garnered escalating attention due to its crucial involvement in cancer development." (PMID 38186575, 2023). "We observed that NLRP7 (n = 8), AIM2 (n = 10), CASP8 (n = 6), GSDMA (n = 5), GSDMB (n = 8), and GSDMC (n = 12) mainly showed hypomethylation in most cancers, and PLCG1 (n = 11), NLRP6 (n = 13), ELANE (n = 11), CASP6 (n = 5), NLRC4 (n = 12), and PYCARD (n = 8) showed hypermethylation in most cancers." (PMID 35246158, 2022). "We found that the CNV in most PRGs is gained in cancer, such as GSDMC, AIM2, and GSDMD." (PMID 35008400, 2022). "Recent studies have shown that AIM2 plays an important dual role in innate immunity and tumorigenesis, but its role in cancer is not fully clarified." (PMID 33842454, 2021). "In summary, our results demonstrated that AIM2 expression was low in BRAF-mutant CRC, and restoration AIM2 expression in BRAF-mutant CRC cells could inhibit cancer cell growth in a caspase-1-dependent manner." (PMID 33842454, 2021). "Absent in melanoma 2 (AIM2) is a member of the interferon‐inducible HIN‐200 protein family, and is associated with inflammation and cancer pathology." (PMID 32725966, 2020). "The nucleotide-binding domain, and leucine-rich repeat containing receptors (NLRs) and absent-in-melanoma 2 (AIM2) are innate immune receptors crucial for initiation and progression of several cancers." (PMID 31186453, 2019). "Based on the literature, we conclude that the anti-cancer properties of lentinan are not mediated by inflammasomes since lentinan did not alter AIM2 mRNA expression nor activation of NLRP3 and NLRC4 inflammasomes." (PMID 28465544, 2017). "Our results suggested that lack of AIM2 expression in HCC cells contributed to disease progression of cancer." (PMID 27167192, 2016). "AIM2 was selected because it was previously thought to be a TSG that is frequently hypermethylated in cancer and because, unlike RUNX3, it becomes unmethylated specifically in the myeloid lineage." (PMID 18820729, 2008). "Although these results pave the way to the application of CRISPR-Cas9 technology to manipulate the AIM2 inflammasome pathway, to date, no experimental data have been obtained by primary cancer cells and/or cancer mouse models to translate them into clinical practice." (PMID 40002808, 2025). "In the second study, which analyzed the gene expression of AIM2 in several cancer types, the authors found that AIM2 was more expressed in cancerous compared to non-cancerous tissues and that its higher expression was correlated to a good prognosis of patients affected by BLCA." (PMID 40002808, 2025). "Absent in melanoma 2 (AIM2), a constituent of the interferon-inducible hematopoietic interferon-inducible nuclear antigens with 200 amino acid repeats protein family, contributes to both cancer progression and inflammasome activation." (PMID 38186575, 2023). "Recent studies suggest that DNA sensors such as AIM2, TLR9, DHX9, DHX36 and adaptor STING may have roles in CRC development, and the other DNA sensors such as DDX41, DDX60, IFI16, and DAI participate in the development of other types of cancers." (PMID 31949493, 2020). "In addition, the interaction of inflammation and cancer is now generally accepted, so it is not strange that AIM2 also plays a vital role in cancers." (PMID 30833546, 2019). "However, there have not been many studies on AIM2 in pan-cancer yet." (PMID 36248785, 2022).